MRAP (melanocortin 2 receptor accessory protein)
Description:
Modulator of melanocortin receptors (MC1R, MC2R, MC3R, MC4R and MC5R). Acts by increasing ligand-sensitivity of melanocortin receptors and enhancing generation of cAMP by the receptors. Required both for MC2R trafficking to the cell surface of adrenal cells and for signaling in response to corticotropin (ACTH). May be involved in the intracellular trafficking pathways in adipocyte cells.
Synonyms: C21orf61; FALP; B27; MRAP1; GCCD2
Tractability: Antibody: UniProt places it where antibodies can reach, with high confidence; its Gene Ontology location is reachable by antibodies, with high confidence; UniProt predicts a signal peptide or a membrane-spanning region.
Gene: Protein-coding gene on chromosome 21 (32,291,813 to 32,314,784, forward strand). Ensembl gene ENSG00000170262.
Subcellular location: Cell membrane; Endoplasmic reticulum membrane
Subcellular location (Human Protein Atlas): Endoplasmic reticulum; Vesicles
Gene Ontology:
Molecular function: corticotropin hormone receptor binding; identical protein binding; protein binding; type 1 melanocortin receptor binding; type 3 melanocortin receptor binding; type 4 melanocortin receptor binding; type 5 melanocortin receptor binding; signaling receptor regulator activity
Biological process: negative regulation of adenylate cyclase-activating G protein-coupled receptor signaling pathway; negative regulation of protein localization to plasma membrane; positive regulation of adenylate cyclase-activating G protein-coupled receptor signaling pathway; protein localization to plasma membrane; regulation of adenylate cyclase-activating G protein-coupled receptor signaling pathway
Cellular component: endoplasmic reticulum; plasma membrane; endoplasmic reticulum membrane
Genetic constraint (gnomAD): Loss-of-function variants: 8 observed, 9.97 expected, observed/expected ratio (o/e) 0.8, 90% interval 0.47 to 1.44. That is too few expected variants to judge how well the gene tolerates losing a copy. Missense variants: 237 observed, 229.39 expected, observed/expected ratio (o/e) 1.03, 90% interval 0.93 to 1.15. Synonymous variants: 95 observed, 100.5 expected, observed/expected ratio (o/e) 0.95, 90% interval 0.8 to 1.12.
Homologues: Orthologues: chimpanzee MRAP (98% identical), macaque MRAP (92% identical), rabbit MRAP (51% identical), mouse Mrap (48% identical), rat Mrap (48% identical).
Diseases named in the same sentence as MRAP in open-access papers:
MRAP is named in the same sentence as 75 diseases in open-access papers, as found by Europe PMC text mining. Sharing a sentence is not in itself a finding about the gene and the disease. The quoted sentences say what the papers report.
glucocorticoid deficiency (10 papers, 2010 to 2024). "Familial glucocorticoid deficiency (FGD) is a rare autosomal recessive disorder as a result of mutation in genes encoding either the ACTH receptor [melanocortin 2 receptor (MC2R)] or its accessory protein [melanocortin 2 receptor accessory protein (MRAP)[." (PMID 19558534, 2010). "Familial glucocorticoid deficiency is caused by variants in the MC2R and MRAP genes." (PMID 39135905, 2024). "Based on the presence of a micropenis and the later onset of hyperpigmentation, along with failed ACTH stimulation test and XY karyotype, we suspected the diagnosis of mutations of NR0B1, CYP11A1, and STAR genes or familial glucocorticoid deficiency (FGD) (MC2R, MRAP, NNT, and AAAS)." (PMID 36407315, 2022). "Familial glucocorticoid deficiency is a rare autosomal recessive genetic disorder which belongs to a group of primary adrenal insufficiency (PAI) and is mainly caused by mutations in the MC2R and MRAP genes." (PMID 32952553, 2020). "Familial glucocorticoid deficiency (FGD) is a rare, autosomal recessive disorder characterised by mutations of the ACTH receptor (melanocortin two receptor, MC2R) or the melanocortin two receptor accessory protein (MRAP), which is required for trafficking MC2R to the cell membrane." (PMID 36060294, 2022). "Patients who have glucocorticoid deficiency due to mutations in MC2 receptors and those who have mutations in MRAP display rather similar phenotypes, but comparison of MC2 receptor and MRAP knockout mice may provide insight into non-adrenal actions of MRAP in the future." (PMID 27486435, 2016). "Here, we report the results of whole-exome sequencing of 43 patients referred to us with a diagnosis of familial glucocorticoid deficiency (FGD) who were mutation negative for MC2R, MRAP, and STAR the most commonly mutated genes in FGD." (PMID 26300845, 2015).
Adrenal insufficiency (7 papers, 2016 to 2026). Insufficient production of steroid hormones (primarily cortisol) by the adrenal glands. "Some of these are localized to certain geographical areas (eg, p.R451W in CYP11A1 in eastern Turkey, c.IVS3ds+1delG in MRAP in western Turkey), which could lead to focused cost-effective clinical genetic testing for patients and families at risk of adrenal insufficiency in these regions." (PMID 26523528, 2016). "In the case of adrenal insufficiency, disrupting mutations in MC2R or the melanocortin 2 receptor accessory protein (MRAP) account for many cases." (PMID 41511347, 2025). "Whereas initially the high ACTH led to the suspicion of primary adrenal insufficiency, the reduced potency of ACTH at the MC2R/MRAP shows that there is actually a secondary adrenal insufficiency." (PMID 35737586, 2022). "Please note that complete KOs of MC2R and MRAP are lethal at birth, and no standard transgenic animal model of adrenal insufficiency currently exists, to our knowledge." (PMID 34236047, 2021). "Mutations in MRAP (encoding melanocortin 2 receptor-associated protein) and NNT (encoding nicotinamide nucleotide transhydrogenase) cause adrenal insufficiency without other features and can only be diagnosed by genetic analysis, as shown here." (PMID 26523528, 2016).
adrenal aplasia (2 papers, 2016 to 2023). "For example, FGD/FGD-like conditions (MC2R, MRAP, NNT gene defects) can present with salt loss suggestive of adrenal hypoplasia, and alterations in STAR and CYP11A1 resulting in partial loss of protein function may have a predominant FGD-like phenotype (17, –, 20)." (PMID 26523528, 2016).
triple-A syndrome (2 papers, 2021 to 2023). Triple A syndrome is a very rare multisystem disease characterized by adrenal insufficiency with isolated glucocorticoid deficiency, achalasia, alacrima, autonomic dysfunction and neurodegeneration. "Defects in MRAP tend to present in early life, whereas presentation with NNT mutations is usually between 6 months and 4 years of age, and triple A syndrome more often in mid-childhood." (PMID 34258490, 2021).
adrenocortical tumour (1 paper, 2022). "Ideally, effects should be observed in cell lines more representative of the adrenal cortex; therefore, the murine Y-1 cell line derived from an adrenocortical tumour, and with endogenous levels of MC2R and MRAP expression, was obtained." (PMID 36515667, 2022).
Down syndrome (1 paper, 2023). "Our study found ATP5O, DYRK1A, MRAP and OLIG2 have high burden in AVSD, especially DYRK1A that is highly and dynamically expressed in the developing heart, and the gain of function rather loss of function of it will leads to AVSD and Down’s syndrome phenotype." (PMID 36816019, 2023).
hypocortisolism (1 paper, 2022). "We found that the variant in our patients resulted in an approximately 100-fold lower potency of ACTH to stimulate MC2R/MRAP, explaining their hypocortisolism." (PMID 35737586, 2022).
Hypoglycemia (1 paper, 2016). A decreased concentration of glucose in the blood. "Hypoglycemia was a frequent finding, and hypoglycemic convulsions at presentation were more common in children with MC2R (22 of 25, 88%) and MRAP (five of nine, 56%) mutations than in children with an alternative diagnosis (5 of 43, 12%) (P < .0001)." (PMID 26523528, 2016).
Hyponatremia (1 paper, 2016). An abnormally decreased sodium concentration in the blood. "Fewer children with NNT (two of seven, 28%), MRAP (two of nine, 22%), and MC2R (2 of 25, 8%) mutations required mineralocorticoid replacement, although four additional children with MC2R defects had transient hyponatremia (sodium 117–133 mmol/L) that resolved without fludrocortisone treatment." (PMID 26523528, 2016).
Sepsis (1 paper, 2021). Sepsis is defined as life-threatening organ dysfunction caused by a dysregulated host response to infection. "Gene expression of MRAP was substantially increased from 1 day of sepsis onwards (p < 0.0001 for all sepsis groups versus healthy control mice)." (PMID 33593393, 2021).
tumor (12 papers, 2015 to 2025). "Therefore, it would be advantageous for tumor therapy if the surface expression of these GPCRs could be altered by MRAP or RAMP." (PMID 37314044, 2024). "In summary, the following marker genes were used for subsequent analysis in supratentorial tumours: RELA, ELL3, FBP2, PCP4L1, and MYO3A for detection of RELA+ tumours; and MRAP, IGF1, CAPS, and WWC1 for detection of YAP1+ tumours." (PMID 34314101, 2021).
infection (10 papers, 2007 to 2024). The state of being infected such as from the introduction of a foreign agent such as serum, vaccine, antigenic substance or organism. "Previous studies have shown that mRAP can prevent infection by blocking Gn from associating with LRP1, thus producing a neutralizing effect." (PMID 37704627, 2023). "Furthermore, mRAP on HEK-293 and HepG2 cells also leaves a residual fraction of infection at high concentrations." (PMID 37704627, 2023).
cancer (6 papers, 2017 to 2025). A tumor composed of atypical neoplastic, often pleomorphic cells that invade other tissues. "MRAP-1 is an ATP-binding cassette transporter protein that confers multiple drug resistance (e.g. to doxorubicin, vincristine and etoposide) in cancer." (PMID 37612278, 2023).
MRAP also shares sentences with these, for which no sentence is quoted: spondyloarthritis (17 papers); Arthritis (15); uveitis (13); ankylosing spondylitis (12); enthesitis (6); glioma (5); Obesity (5); psoriasis (5); reactive arthritis (5); spondylitis (5); AIDS (4); anterior uveitis (4); glioblastoma (3); HIV-1 infection (3); inflammatory bowel disease (3); juvenile idiopathic arthritis (3); psoriatic arthritis (3); autoimmune disease (2); Behçet’s disease (2); brucellosis (2); colitis (2); Hepatitis (2); hepatocellular carcinoma (2); neuroblastoma (2); pancreatic cancer (2); primary adrenal insufficiency (2); rheumatoid arthritis (2); sacroiliitis (2); viral infections (2); acute myeloid leukemia (1).
A further 32 diseases each share a sentence with MRAP in 1 paper.